AHSG (alpha 2-HS glycoprotein)
Diseases named in the same sentence as AHSG in open-access papers (continued):
Sharing a sentence is not in itself a finding about the gene and the disease.
glioma (6 papers, 2015 to 2024). A benign or malignant brain and spinal cord tumor that arises from glial cells (astrocytes, oligodendrocytes, ependymal cells). "A biomarker panel consisting of AACT, TSP4, MDHM, CALR, LEG1, and AHSG showed the best diagnostic performance for the detection of gliomas, with an area under the curve (AUC) value of 0.958." (PMID 32922940, 2020). "ROC curve analysis showed that the combination of six urinary proteins (AACT, TSP4, MDHM, CALR, LEG1, and AHSG) can effectively discriminate the gliomas patients from healthy controls with the AUC of 0.952." (PMID 32922940, 2020). "After targeted proteomics validation, we identified a biomarker panel (AACT, TSP4, MDHM, CALR, LEG1, and AHSG) with an area under the curve (AUC) value of 0.958 for the detection of gliomas." (PMID 32922940, 2020). "Interestingly, AACT, GELS, TENA, LEG1, and AHSG had been reported as potential CSF or blood biomarkers of gliomas, which indicates the validity of our results." (PMID 32922940, 2020). "Interestingly, AACT, LEG1, and AHSG are also potential cerebrospinal fluid or blood biomarkers of gliomas." (PMID 32922940, 2020). "Compared with healthy controls, the abundance of urinary AACT increased in gliomas patients, while the abundance of urinary TSP4, MDHM, CALR, LEG1, and AHSG decreased in gliomas patients." (PMID 32922940, 2020). "Several serum biomarkers-YKL40, MMP9, B-chain of α2-Heremans-Schmid glycoprotein (AHSG), Haptaglobin α2, Osteopontin and IGFBP2 have been reported to identify glioma." (PMID 26390214, 2015). "It was observed that urinary AACT and GELS were significantly upregulated in glioma patients compared to healthy controls, whereas urinary TSP4, MDHM, RINI, CALR, TENA, LEG1, and AHSG were significantly downregulated in glioma patients compared to healthy controls." (PMID 32922940, 2020). "Interestingly, AACT, LEG1, and AHSG are blood or CSF biomarkers of gliomas, and CALR is correlated with glioma grade and patient survival." (PMID 32922940, 2020).
hepatocellular carcinoma (6 papers, 2014 to 2025). A malignant tumor that arises from hepatocytes. "AHSG expression of hepatocellular carcinoma showed downward trend (1.43 fold; P = 0.09) after OGD/R." (PMID 34168538, 2021).
renal fibrosis (5 papers, 2021 to 2024). A final common manifestation of a wide variety of chronic kidney diseases characterized by glomerulosclerosis and tubulointerstitial fibrosis. "AHSG (Alpha 2-HS Glycoprotein), also known as fetuin-A, is a multifunctional protein secreted by both liver and adipose tissue; it came into our notice as it had been reported to attenuate renal fibrosis by antagonizing TGF-β signaling." (PMID 37004048, 2023).
intrauterine growth restriction (4 papers, 2014 to 2024). "A study by Karamessinis reported alterations at the post-translational modification level in alpha-2-HS glycoprotein (fetuin-A) protein in intrauterine growth restriction cases, and this glycoprotein is inextricably bound to fetal growth, cell replication, and osteogenesis." (PMID 36009368, 2022).
lung carcinoma (4 papers, 2014 to 2025). "Exosomal proteomes have identified several exosomal proteins, including CD317, EGFR, leucine-rich a2-glycoprotein (LRG1), alpha-2-HS-glycoprotein (AHSG), and extracellular matrix protein 1 (ECM1), that hold the potential to serve as indicators for lung cancer early detection." (PMID 40559625, 2025).
pancreatic cancer (4 papers, 2017 to 2024). "In addition, studies have reported increased concentrations of C3, AHSG, and SERPINF1 proteins in the peripheral blood of pancreatic cancer patients." (PMID 37759310, 2023). "However, several other known acute-phase reactants were found not to be elevated (e.g., AHSG, SERPINA3, ITIH4, FN, F2, F8, SAP, and CD163), arguing that there may be some specificity in the inflammatory response to pancreatic cancer." (PMID 29232830, 2017).
anemia (3 papers, 2013 to 2023). A reduction in the number of red blood cells, the amount of hemoglobin, and/or the volume of packed red blood cells. "In addition, alpha-2-HS-glycoprotein and LRG1 were the most prospective candidates for different myelodysplastic syndrome subgroups, including refractory cytopenia with multilineage dysplasia, refractory anemia or refractory anemia with ringed sideroblasts, etc." (PMID 35095520, 2021).
Caffey disease (3 papers, 2020 to 2022). Caffey disease is an osteosclerotic dysplasia characterized by acute inflammation with massive subperiosteal new bone formation usually involving the diaphyses of the long bones, as well as the ribs, mandible, scapulae, and clavicles. "Furthermore, an autosomal recessive type of Caffey disease was recently described, reporting a nonsense variant in the AHSG gene that encodes alpha 2-HS glycoprotein involved in the formation of bone tissue." (PMID 32033218, 2020). "This phenotype was reminiscent of Caffey disease, an infantile disorder characterized by excessive new bone formation (hyperostosis), and indeed of a recent case report carrying a nonsense mutation in the AHSG gene, which resulted in complete fetuin-A deficiency in the affected child." (PMID 35403906, 2022).
experimental autoimmune encephalomyelitis (3 papers, 2017 to 2025). An autoimmune demyelinating disease of the central nervous system that is produced experimentally in animals by the injection of homogenized brain or spinal cord in Freund's adjuvant. "In addition, the deficiency of AHSG was reported to protect against experimental autoimmune encephalomyelitis in the mouse model by dampening innate immunity." (PMID 41219226, 2025).
liver cancer (3 papers, 2007 to 2022). An epithelial or non-epithelial malignant neoplasm that arises from the liver. "Serum concentration of fetuin A/α2HS-glycoprotein (AHSG) is a good indicator of liver cell function and 1-month mortality in patients with alcoholic liver cirrhosis and liver cancer." (PMID 17394649, 2007). "Previous studies have demonstrated that AHSG is highly expressed in liver cancer tissues compared to adjacent non-tumor tissues, which is consistent with our screening results." (PMID 35935258, 2022).
liver cirrhosis (3 papers, 2017 to 2023). "AHSG is overexpressed in the liver and has been associated with uremia and liver cirrhosis." (PMID 28974199, 2017). "Expression pattern of AHSG accurately predicts the prognosis of liver cirrhosis and hepatocellular cancer." (PMID 34907282, 2021).
obstructive sleep apnea (3 papers, 2015 to 2022). "In network 1 (upper network), we found a link to both Alb and AHSG (alpha-2-HS-glycoprotein), which is quite interesting because this protein has been recently linked to obstructive sleep apnea patients with cardiovascular diseases as a salivary biomarker." (PMID 26161641, 2015).
alcoholic cirrhosis (2 papers, 2007 to 2023). "Serum AHSG concentration is a reliable and sensitive indicator of 1-year mortality in patients with alcoholic liver cirrhosis that compares well to the predictive value of CP score and may further improve that of MELD score." (PMID 17394649, 2007).
ankylosing spondylitis (2 papers, 2016 to 2019). An autoimmune chronic inflammatory disorder characterized by inflammation in the vertebral joints of the spine and sacroiliac joints. "AHSG expression is decreased in patients with ankylosing spondylitis, which may be one reason for pathological osteogenesis." (PMID 30881463, 2019).
autoimmune disease (2 papers, 2016 to 2022). A disorder resulting from loss of function or tissue destruction of an organ or multiple organs, arising from humoral or cellular immune responses of the individual to their own tissue constituents. "Changes in the glycosylation of Alpha-2-macroglobulin and Alpha-2-HS-glycoprotein have been associated with cancer and autoimmune diseases." (PMID 26999365, 2016).
head and neck cancer (2 papers, 2014 to 2021). A primary or metastatic malignant neoplasm affecting the head and neck. "The alpha-2-HS-glycoprotein is known as an immune-reactive protein that was determined to be smoking- and age-associated with the development of head and neck cancers." (PMID 34945026, 2021). "The consistent association of chronic smoking shows an immune reactivity status that changes the serum levels of alpha-2-HS-glycoprotein in head and neck cancer patients." (PMID 34945026, 2021).
infertile (2 papers, 2021 to 2025). "Various autoantibodies, including anti-histone H1.2 and anti-alpha 2-HS glycoprotein, were found in the peritoneal fluid or serum in infertile patients with endometriosis, affecting 60% of women with endometriosis-associated infertility." (PMID 40130159, 2025).
insomnia (2 papers, 2021 to 2022). A sleep disorder characterized by difficulty in falling asleep and/or remaining asleep. "On the other hand, through Western blot experiments, we verified that the expression of FGG, FGB, FGA, APOB, F2, and HP was upregulated in insomnia patients with wakefulness compared with the control, while the expression of A2M, AHSG, and APOA1 was downregulated." (PMID 33511209, 2021). "Among them, HP, MMP9, FGA, FGB, and FGG were validated as upregulated, and APP, AHSG, and IGF1 were downregulated in patients with insomnia." (PMID 35958162, 2022). "In the results, HP, FGA, FGG, FGB, and MMP9 were upregulated in patients with insomnia, and FN1, APP, EGF, AHSG, and IGF1 were downregulated compared with controls." (PMID 35958162, 2022).
lipid metabolism disorder (2 papers, 2013 to 2020). "In addition, it has been confirmed from extensive studies of genetic epidemiology that polymorphisms in the gene encoding fetuin-A, the alpha-2-Heremans-Schmid glycoprotein (AHSG) gene, may affect glucose and lipid metabolism disorders’ pathophysiology progression in some higher-risk groups." (PMID 32326594, 2020).
malaria (2 papers, 2012 to 2015). Malaria is a serious and sometimes fatal disease caused by a parasite that commonly infects a certain type of mosquito which feeds on humans. "Some of these malaria serum-reactive proteins could be detected in both non-infected and infected serum, including AHSG, A1BG, and Apo-AI." (PMID 25656928, 2015).
malignant ovarian tumors (2 papers, 2022 to 2023).
preeclampsia (2 papers, 2022). Preeclampsia is a hypertensive disorder of pregnancy that is characterized by new-onset hypertension with proteinuria presenting after 20 weeks of gestation, and depending on mild or severe forms may initially present with severe headache, visual disturbances, and hyperreflexia. "AHSG, also known as fetuin-A, has been proven to present a negative correlation with coagulation activation in preeclampsia." (PMID 36224755, 2022).
Vestibular schwannoma (2 papers, 2022 to 2023). A vestibular schwannoma (also known as acoustic neuroma, acoustic neurinoma, or acoustic neurilemoma) is a benign, usually slow-growing tumor that develops from the VIIIth cranial nerve supplying the inner ear. "AHSG is secreted and acts as peptidase and kinase inhibitors involved in the acute-phase response; it is present in the perilymph of vestibular schwannoma patients, and its level is significantly correlated with the insurgence of hearing loss." (PMID 37627098, 2023).
Adamantinomatous Craniopharyngioma (1 paper, 2023). A craniopharyngioma consisting of broad strands, cords and bridges of a multistratified squamous epithelium with peripheral palisading of nuclei. "AHSG has also been detected in the cystic fluid of adamantinomatous craniopharyngioma where it may play a role in the deposition of calcium." (PMID 37627098, 2023).
aneurysm (1 paper, 2023). Bulging or ballooning in an area of an artery secondary to arterial wall weakening. "The lower expression of AHSG protein in BB samples compared to HC samples, suggests the potential role of AHSG in aneurysm formation." (PMID 36922793, 2023).
cataract (1 paper, 2021). Partial or complete opacity of the crystalline lens of one or both eyes that decreases visual acuity and eventually results in blindness. "We considered that the alpha-2-HS-glycoprotein could be an aqueous-specific marker of cataract risks that is highly associated with smoking." (PMID 34945026, 2021). "The alpha-2-HS-glycoprotein was significantly differently expressed between risk groups and cataract controls and could be a potential aqueous protein marker for detecting smoking and DM cataract risk factors." (PMID 34945026, 2021). "However, there is scarce evidence demonstrating a relationship between the alpha-2-HS-glycoprotein and cataract disease in human beings to date." (PMID 34945026, 2021).
cystic tumors (1 paper, 2023). "We detected in the cystic fluid of all tumors some proteins that are already known to play a role in one or more of the cystic tumors studied: gelsolin (GSN), haptoglobin (HP), alpha-2-HS-glycoprotein (AHSG) and alpha-1-antichymotripsin (AACT)." (PMID 37627098, 2023).
dilated cardiomyopathy (1 paper, 2023). Cardiomyopathy which is characterized by dilation and contractile dysfunction of the left and right ventricles. "AHSG was additionally proposed as a potential biomarker for the differential diagnosis of ischemic cardiomyopathy from dilated cardiomyopathy, where low levels of AHSG were observed in patients with ischemic cardiomyopathy." (PMID 36922793, 2023).
gastritis (1 paper, 2022). Inflammation of the stomach. "We find these proteins in different subsets of our comparative analyses, e.g., APOA1 and AHSG in GC vs. U, and FGA in NGM vs. GC, but, with the exclusion of the shared proteins with the gastritis and U datasets, they are not significant anymore." (PMID 35566209, 2022).
hearing loss (1 paper, 2018). "Our present study identified alpha-2-HS-glycoprotein as an independent factor for hearing loss and since it was part of the stable section of the proteome an interesting candidate as possible biomarker." (PMID 29856847, 2018).
Immunodeficiency (1 paper, 2021). Failure of the immune system to protect the body adequately from infection, due to the absence or insufficiency of some component process or substance. "Three of the factors were expressed at higher levels in ambiguous than in unambiguous cases—AHSG, TFRC, DHX9—and are involved in inflammation, innate immunity, and immunodeficiency, which are components of past infections." (PMID 33582300, 2021).
latent infections (1 paper, 2025). "Early markers, such as Gc-globulin and alpha-2-HS-glycoprotein, may facilitate the detection of latent infections; the infected individual carries the pathogen but does not exhibit overt clinical signs." (PMID 40646861, 2025).
lung diseases (1 paper, 2017). "A set of three most significantly upregulated proteins (HBB, CRP and SERPINA1) and four most significantly downregulated proteins (APOA2, AHSG, KNG1 and AMBP) were selected for validation in an independent cohort of IPF and other lung diseases using ELISA test." (PMID 28122020, 2017).
necrotizing enterocolitis (1 paper, 2025). Necrotizing enterocolitis (NEC) is a devastating disease that affects mostly the intestine of premature infants. "The findings of this study unravel a previously unrecognized regulatory axis involving AHSG, BHMT2, and MAT1A that orchestrates macrophage polarization and contributes to the exacerbation of necrotizing enterocolitis." (PMID 41219226, 2025).
neuroblastoma (1 paper, 2017). Neuroblastoma (NB) is the most common solid, extracranial childhood tumor. "Among them, two N-linked glycoproteins, alpha-2-HS-glycoprotein (AHSG) and hemopexin (HPX), markedly exhibited the WN1316-mediated cytoprotection against oxidative injury in differentiated neuroblastoma SH-SY5Y cells." (PMID 29016670, 2017).
open-angle glaucoma (1 paper, 2021). Chronic outflow obstruction of the eye's drainage canals that can lead to increased internal eye pressure and optic nerve damage. "The alpha-2-HS-glycoprotein inhibits bone morphogenetic proteins that are changed in the TM in open-angle glaucoma." (PMID 34945026, 2021). "This evidence suggests the potential interactions of the alpha-2-HS-glycoprotein with multiple proteins that are important in open-angle glaucoma." (PMID 34945026, 2021).
rectal cancer (1 paper, 2014). A primary or metastatic malignant neoplasm that affects the rectum. "Furthermore, alpha-2-HS-glycoprotein levels can be used to distinguish between colon and rectal cancers." (PMID 24618180, 2014).
renal cell carcinoma (1 paper, 2025). "Alpha-2-HS-glycoprotein (AHSG) is a novel renal cell carcinoma biomarker gene promoting cancer cell proliferation by regulating the transforming growth factor-β signaling pathway." (PMID 40869014, 2025).
sarcoma (1 paper, 2024). A usually aggressive malignant neoplasm of the soft tissue or bone. "The Survival Genie web-based platform was then used to associate expression of TCN2 and AHSG with overall survival in publicly available OSA (TARGET-OS) and sarcoma (TCGA-SARC) bulk tumor RNA-sequencing datasets." (PMID 39493449, 2024).
virus infection (1 paper, 2012). "Although AHSG is involved in the inflammation mechanism, there have not been reports on its direct involvement in virus infection." (PMID 22506017, 2012).
X-linked hypophosphatemia (1 paper, 2019). X-linked hypophosphatemia (XLH) is a hereditary renal phosphate-wasting disorder characterized by hypophosphatemia, rickets and/or osteomalacia, and diminished growth. "Interestingly, two skeletal disease mouse models also show similarity to the androgen receptor knockout; the Phex-deficient Hyp mouse model of X-linked hypophosphatemia and the AHSG knockout model of model of slipped capital femoral epiphysis (SCFE)." (PMID 30481257, 2019).
cardiovascular disease (44 papers, 2008 to 2025). "Plasma Fetuin-A level has been associated with cardiovascular disease and AHSG variants have been previously associated with AD." (PMID 23894628, 2013). "The genes encoding human fetuin-A (AHSG) and human adiponectin (ADIPOQ), which is almost exclusively secreted from adipose tissue and represents an important determinant of whole-body insulin sensitivity and cardiovascular disease, are located next to each other on chromosome 3q27." (PMID 18335040, 2008). "In cardiovascular disease, the levels of AHSG (alpha 2-HS glycoprotein) are significantly lower than in controls." (PMID 35958162, 2022).